SHH (sonic hedgehog signaling molecule)
Diseases named in the same sentence as SHH in open-access papers (continued):
Sharing a sentence is not in itself a finding about the gene and the disease.
tumor (continued). "A significant correlation was also found between SHH expression and a lower tumor grade, suggesting that SHH signaling is relevant not only in late stages to promote progression and recurrence but also in early stages to enhance tumor growth and proliferation." (PMID 31027259, 2019). "Tumor driven by SHH are particularly aggressive and frequently resistant to SHH inhibitors." (PMID 31277672, 2019). "Together, these results demonstrated that EIF5A and sHH signalling pathway may be involved in and were necessary for tumour growth in PC, which is consistent with our pre‐primary work." (PMID 30761741, 2019). "To evaluate the impact of FGFR and SHH signaling on tumor cell growth and tissue invasion, we performed organotypic cerebellum slice-tumor cell co-culture experiments in the absence and the presence of exogenously added bFGF, SAG, or with a combination of both." (PMID 31835472, 2019). "IDHWT tumours also showed variation in SHH (16%; 6/38) and NOTCH (8%; 3/38) pathways." (PMID 32082376, 2019). "Inhibition of EIF5A and sHH signalling pathway could suppress PC cells proliferation and tumour growth." (PMID 30761741, 2019). "SHH signaling is one of the major molecules regulating CSCs in the progression of the tumor." (PMID 30899425, 2019). "Our previous analysis of protein and gene expression patterns in DIPG tumor tissue specimens revealed two molecular subgroups of DIPG with relative activation of either Sonic Hedgehog (SHh) or MYCN signaling, with TNC hypomethylation and increased expression in the SHh group." (PMID 31092287, 2019). "We hypothesised that inhibiting the SHH pathway could lead to an increase in the number of cells with clonogenic tumour cells within, potentially tumour-initiating cells." (PMID 30645190, 2019). "Here, we demonstrated a novel role for SHH in the development of the tumor vasculature." (PMID 31744214, 2019). "However, PTCH-positive tumor blood vessels were observed abundantly in sites close to the cancer parenchyma where SHH was strongly expressed." (PMID 31744214, 2019). "In ER-positive BC, increased GLI1 expression correlated with early disease onset, increased SHH expression, high Ki-67 index, higher histological grade, advanced tumor stage, lymph node involvement, metastasis, and shorter overall survival and disease-free survival." (PMID 31027259, 2019). "Finally, we show both in tumor tissue and in cell lines that Stat3 supports SHH signaling which is potentiated by co-treatment with the STAT3 activating cytokine IL-6." (PMID 31683879, 2019). "This raises the question of a dichotomous pro-invasive/anti-proliferative function of bFGF in MB tumors with activated SHH signaling that may impact on the growth and the dissemination of the tumor cells." (PMID 31835472, 2019). "Therefore, SHH signaling affects not only tumor growth but also the cells that make up the cancer stroma and is an important pathway in the TME." (PMID 31744214, 2019). "Despite this similarity, myofibroblasts-depleted tumors showed decreased tumor vasculature implying that increased vascularity in SHH KO studies may be specific to suppression of SHH signaling." (PMID 30108679, 2018). "GLI1 has been demonstrated to be a mediator of the SHH signal in vertebrates by binding to the promoter region of several target genes involved in different cellular processes, such as G1 cell cycle progression, tumor formation, and progression." (PMID 30423843, 2018). "Tumor-derived HH ligands, such as sonic hedgehog (SHH), bind to their cognate receptor Patched1 (PTCH1) on stromal fibroblasts, releasing its repression of Smoothened (SMO) and allowing for activation of downstream glioma-associated oncogene homolog (GLI) transcription factors." (PMID 30456390, 2018). "However, complete loss of SHH signaling in fibroblasts (GAS1−/−, BOC−/− and CDON−/−) abrogated angiogenesis and tumor growth." (PMID 30108679, 2018).
tumor (continued). "To date, it remains unclear as to whether aggressive tumor growth is attributable to events downstream of SHH/GLI pathway activation or to other yet unidentified pathways." (PMID 29137400, 2017). "SHH ligands secreted by tumor cells positively regulate signaling in the surrounding tumor stroma, whereas stroma fibroblast cells can also serve as a resource for SHH ligands, which then activate SHH signaling in tumor cells through an inverse paracrine way12." (PMID 29042665, 2017). "This is illustrated by tumor intervention studies in a GEMM of PDAC, which showed that therapeutic inhibition of paracrine Sonic Hedgehog (SHH) signaling reduced desmoplastic tumor stroma and increased tumor vasculature, resulting in enhanced delivery of gemcitabine to tumors." (PMID 28028012, 2017). "First, we tested several SHH pathway inhibitors on the tumor cells of the patient in vitro." (PMID 29371980, 2017). "They showed in a mouse model that inhibition of the stroma sonic hedgehog (SHH) pathway could increase vascularization, leading to increased delivery of chemotherapeutic agents to tumours and greater anti-cancer efficacy." (PMID 28352075, 2017). "Collectively, these data demonstrate that HDAC1/2 are regulated by the Hh signaling to support tumor cell proliferation and argue that a selective pharmacological targeting of these deacetylases may counteract SHH-MB growth." (PMID 28276480, 2017). "In addition, the non-transformed NIH-3T3 mouse embryonic fibroblasts have been extensively utilized in investigations on tumor-stroma interactions in the microenvironment as well as SHH signaling." (PMID 29042665, 2017). "We next tested whether SHH could be the ligand responsible for Gli1 expression near tumor cells by examining ShhnlacZ expression in PB-MYC and TRAMP tumors." (PMID 27935821, 2017). "In addition to the increased expression of RANKL by SHH recreated by tumor cells, we previously observed a cooperative effect of the PTHrP pathway in osteoblasts on osteoclastogenesis in the context of SHH treatment." (PMID 27007126, 2016). "SHH gene expression was significantly higher in most tumor tissues (P = 0.002)." (PMID 27039174, 2016). "Likewise, the results showed that most LAC cell lines (except for A549) showed a significantly reduced HHIP, but comparable GLI1 and SHH mRNA levels as compared to non-tumor lung epithelial cells BEAS-2B or NL20." (PMID 27015549, 2016). "We found that SHH pathway genes are similarly upregulated in the primary tumor as well as in PDX." (PMID 26938241, 2016). "Even more remarkable changes were noted on pathological observation of resected tumors: besides significantly decreased tumor size, the presence of intact tumor cells in tumor nests was significantly decreased in the group treated with SHH inhibitors (p < 0.01)." (PMID 26716648, 2016). "We hypothesized that the production of SHH by tumor cells would promote a paracrine signaling pathway and stimulate hedgehog signaling in bone marrow host cells." (PMID 27007126, 2016). "Likewise, SKOV3 and CAOV-3 tumor cells demonstrated significant induction of SHH while COV318 cells demonstrated significant induction of IHH." (PMID 26755648, 2016). "Finally, we subclassified the tumor obtained from the primary tumor sample as well as from PDX specimen for the expression of specific marker genes restricted to SHH, Wnt, Non SHH/Non Wnt pathway." (PMID 26938241, 2016). "Therefore, when cyclopamine blocks SHH signaling to decrease Gli-1 mRNA expression, a corresponding decrease in Bcl-2 mRNA can occur, which can promote apoptosis of tumor cells." (PMID 26716648, 2016). "Despite the known continued synthesis of SHH in the adult brain and by some GBM cells, it remains unclear whether ciliary SHH signaling contributes to GBM tumor growth." (PMID 26760767, 2016). "The activated SHH might be responsible for the dying cells stimulating living tumor cell growth, and SHH signaling might act upstream of the Wnt signaling pathway." (PMID 25713298, 2015).
tumor (continued). "As such, CD271+ cells may be less responsive to SHH pathway inhibition emphasizing the importance of understanding tumor heterogeneity when attempting to dissect the complex factors leading to targeted therapy." (PMID 26497209, 2015). "Collectively, our data suggest that Ptch2 upregulation in endothelial cells and further ligand activation cause an imbalanced HH signaling, that can account for the observed vascular dysfunctions and barrier disruption, while sparing SHH positive impact on tumor cell expansion." (PMID 26635611, 2015). "In summary, our results provide a new understanding of the complicated crosstalk between the SHH and Wnt signaling pathways during tumor cell repopulation, which might play an important role in tumor growth and relapse after radiotherapy or chemotherapy." (PMID 25713298, 2015). "However, Wnt signaling and its interaction with SHH signaling in dying tumor cells, as well as their roles in stimulating tumor cell repopulation, has not been reported." (PMID 25713298, 2015). "Our previous study demonstrated that SHH was activated in dying cells and that the manipulation of SHH signaling could influence tumor repopulation." (PMID 25713298, 2015). "Moreover, SHH and GLI-1 expression were also up-regulated in tumor-associated stromal cells in PC tissue specimens." (PMID 25682877, 2015). "We therefore deduced that SFRP1 might be the link between Wnt and SHH signaling pathways during tumor repopulation." (PMID 25713298, 2015). "Thus together these data support the view that in SHH/CDON-expressing tumor cells, SHH constitutively inhibits CDON-induced apoptosis." (PMID 23940460, 2013). "Aberrant activation of the SHH signaling pathway can result in tumor formation." (PMID 23835807, 2013). "In summary, based on the existing literature on the role of SHH signaling in tumor growth and the radiation response and our findings in this study, we believe that the SHH signaling plays an important role in tumor growth and relapse during radiotherapy or chemotherapy." (PMID 23762282, 2013). "Moreover, the dying cell stimulation of living tumor cell growth was enhanced by the addition of SHH signaling agonists and inhibited by SHH signaling antagonists." (PMID 23762282, 2013). "Given the significantly up-regulated SHH pathway activity in irradiated cells, we examined whether manipulation of the SHH pathway would inhibit or promote dying tumor cell stimulated living tumor cell growth." (PMID 23762282, 2013). "Thus, targeting CDON/SHH interaction triggers tumor cell death and tumor growth inhibition by engaging CDON pro-apoptotic activity." (PMID 23940460, 2013). "Since the mechanisms underlying tumor accelerated repopulation during radiotherapy are not well understood, we aim to investigate a role for the well-established SHH pathway in the tumor cell proliferation after radiotherapy process." (PMID 23762282, 2013). "Moreover, they are consistent with a model in which epigenetic changes help to drive BCC tumor growth through deregulation of the WNT pathway, upon initiation of growth by mutations affecting SHH signaling." (PMID 23284750, 2012). "Our findings suggest that inhibition of tumor angiogenesis via suppression of the SHH pathway might be one of the mechanisms by which Scutellaria barbata D. Don can be effective in the treatment of cancers." (PMID 22949805, 2012). "In addition, EESB treatment suppresses the expression of key mediators of the SHH pathway in tumor tissues, which in turn resulted in the inhibition of tumor angiogenesis." (PMID 22949805, 2012). "Therefore, our results provide evidence for a pivotal and orchestral role for SHH signaling pathway in the constitutive activation of oncogenic pathways leading to sustained tumor growth." (PMID 20015350, 2009). "Thus, the SHH signaling pathway is constitutively expressed and activated in tumor cells and independently of VHL expression." (PMID 20015350, 2009).
tumor (continued). "Interestingly, SHH signaling inhibition induced substantial tumor regression in nude mice, and the inhibitory effect on tumor growth was long-lasting after treatment arrest." (PMID 20015350, 2009). "The anti-tumor effect obtained following the first protocol prompted us to assess in a second protocol whether we could observe tumor regression with cyclopamine by increasing the overall dose of the SHH inhibitor in tumor-bearing mice." (PMID 20015350, 2009). "Importantly, inhibition of the SHH pathway induced tumor regression in nude mice through inhibition of cell proliferation and neo-vascularization, and induction of apoptosis but not senescence assessed by in vivo studies, immunoblot and immunohistochemistry." (PMID 20015350, 2009). "Thus in individual patients, tumor expression of Perlecan and SHH are correlated, in agreement with the co-localization of Perlecan and SHH in tissue microarrays." (PMID 16507112, 2006). "Furthermore, recent reviews indicate that CAFs, including resident fibroblasts and mesenchymal stem cells, contribute to tumor progression by remodeling the extracellular matrix and modulating immune responses, with SHH signaling being a key factor in their activation." (PMID 40635786, 2025). "In addition, whether the regulation of CAF-exo in PMN formation and distant metastasis through the GREM1/SHH/FGF4 axis can similarly influence orthotopic tumor properties to promote the distant metastasis needs to be further investigated." (PMID 40849639, 2025). "SHH signaling exerts a direct effect on the proliferation and maintenance of stem cells, and their alteration in stroma paracrine signaling could promote a favorable microenvironment for tumor viability." (PMID 40729247, 2025). "PTCH1 is a receptor for SHH, and the activation of SHH signaling exerts a direct effect on the proliferation and maintenance of stem cells; alteration of its signaling could promote a favorable microenvironment for the maintenance of tumor viability." (PMID 40729247, 2025). "SMO mutations may sometimes prevent long-term therapeutic benefits from occurring; in other circumstances, mutations in downstream components of the SHH pathway (for instance, MYCN or GLI2 amplifications) or in other pathways might render tumor cells resistant to these medications." (PMID 38391759, 2024). "Preferential activation of SHH in TICs could be possibly due to the distinct gene expression profile of cancer stem-like cells from that of differentiated cancer cells within a heterogenous tumour tissue." (PMID 38317186, 2024). "Moreover, among the various signaling pathways, the Sonic hedgehog (SHH) signaling pathway is implicated in multiple aspects of HCC, including cancer development, growth, invasiveness, recurrence, metastasis, the tumor microenvironment, and the maintenance of its cancer stem cells." (PMID 38730691, 2024). "Additionally, DNMT1 pharmacological inhibition alone and in combination with SMO inhibition effectively inhibits tumor growth in murine and human SHH-MB cell models and prolongs survival of SHH-MB mouse models by inhibiting SHH signaling output downstream of SMO." (PMID 39107797, 2024). "Furthermore, NRF2 might mediate the function of tumor-initiating cells (T-ICs) by upregulating SHH expression." (PMID 38730691, 2024). "FISH and single-cell sequencing analyses concur that only a minority of RCMB56 primary tumor cells harbored high-copy amplification, and clustering on single-cell data suggests that these cells express a distinct transcriptional and epigenetic profile, including a canonical marker of SHH signaling." (PMID 37945900, 2023). "Gene set enrichment analysis (GSEA) suggested that Id1 deletion in TAMs resulted in the inhibition of focal adhesion kinase (FAK) and Yes-associated protein (YAP) signaling pathways but not other tumor stemness associated signaling such as Notch, Wnt/β-catenin and Sonic hedgehog (SHH) pathway 29,30." (PMID 37996458, 2023).
tumor (continued). "In 2014, the deletion of SHH in mouse models and the pharmacological reduction of SHH pathways using vismodegib was pointed out by scientists not only did not have the desired tumor suppressive effect but, in some contexts, accelerated the tumor process because it reduced the stromal desmoplasia." (PMID 37784082, 2023). "No statistical association was found between SHH protein immunoexpression and tumor stage." (PMID 37964226, 2023). "In addition, studies have shown that the expression of VEGF in ACP cells can promote tumor angiogenesis and increase microvascular density; however, whether the SHH pathway affects tumor blood supply in ACP through VEGF has not been clarified." (PMID 36387067, 2022). "Carballo and co-workers presented data showing that SHH pathway inhibition with cyclopamine interferes with GBM cell viability and also suggested that cyclopamine inhibition of the SHH pathway prior to TMZ treatment could reduce the aggressiveness of the tumor cells by sensitizing the GSCs to TMZ." (PMID 36010607, 2022). "Taken together, Snr1 knockdown in engrailed expressing cells causes aberrant hedgehog and Notch signaling and is associated with formation of tumor-like structures in the fly model, suggesting that SMARCB1-deficiency may have a similar role on SHH and Notch activation in human ATRT–SHH." (PMID 35501487, 2022). "Additionally, the SHH signaling pathway might have important implications for the development and prognosis of tumor diseases." (PMID 35933378, 2022). "The number and time of tumor formation were related to the degree of mtDNA consumption, and long-term depletion leads to the damage of mtDNA replication thus inducing the expression of early development and survival-promoting markers, including sonic hedgehog (SHH)." (PMID 36139663, 2022). "Together, these findings provide insight into the roles of SHH, PlGF, and Nrp1 in SHH subgroup MB, and as PlGF is dispensable during development, they support the idea that this SHH tumor and PlGF interaction may be used as a therapeutic approach for this pediatric tumor." (PMID 34436033, 2021). "In order to unravel pathway alterations in IO-MEPLs, we analyzed gene expression data from tumor samples of 8 previously genetically characterized human IO-MEPLs along with a set of 16 intracranial embryonal tumors comprising ETMRs and MBs, including the molecular groups SHH-, WNT-, and Group 4-MB." (PMID 34785636, 2021). "Given that SHH signaling was significantly suppressed in Rack1‐deficient GNPs,24 and deletion of Rack1 in SHH‐MB could significantly suppress the proliferation of tumor cells, therefore, we asked whether the absence of Rack1 in MB tumor cells could also induce the inactivation of SHH signaling." (PMID 34480519, 2021). "Importantly, we found SHH and WNT signaling pathway activities were reduced with SPOP downregulation, suggesting that the tumor-promoting function of SPOP stands in activation of the SHH and WNT signaling pathways, which have been shown to be aberrantly activated in ccRCC35,36." (PMID 34021128, 2021). "The role of SHH during tumor-associated angiogenesis has not been clarified in OSCC." (PMID 31744214, 2019). "Additionally, our studies also showed that SHH was expressed in tumor blood vessels." (PMID 31744214, 2019). "In addition, Oxy210 treatment significantly reduced the endogenous gene expression for SHH in A549 cells, indicating that both the ligand production emanating from tumor cells as well as the stromal response in fibroblasts can be targeted by Oxy210, in a potentially synergistic manner." (PMID 31652618, 2019). "Thus, SHH signaling had both autocrine and paracrine effects on tumor angiogenesis in OSCC." (PMID 31744214, 2019). "Besides, according to Samadani's research, SHH signaling may contribute to the survival of tumor cells, the exact role and mechanism are still unclear." (PMID 31898580, 2019).